AFP (alpha fetoprotein)
Diseases named in the same sentence as AFP in open-access papers (continued):
Sharing a sentence is not in itself a finding about the gene and the disease.
liver cancer (continued). "Numbers and percentages of immune cells, concentrations of CRP and liver cancer biomarkers (AFP, CEA and CA19-9) were detected in the blood of the two groups of patients." (PMID 36290905, 2022). "AFP + CA-125 has the highest specificity, and is of great significance for the diagnosis of ocular metastasis from liver cancer." (PMID 36199582, 2022). "At present, the main indicator of primary liver cancer (PLC) in clinical diagnosis is alpha fetoprotein (AFP), which has been widely used in the general survey and screening of high-risk groups." (PMID 34979994, 2022). "The examination of GPC3 and AFP in blood samples is currently used for the diagnosis of patients with liver cancers." (PMID 36551548, 2022). "The guidelines for the diagnosis and treatment of primary liver cancer (2020) specify AFP as a common and important index for diagnosis of liver cancer and efficacy testing." (PMID 36578484, 2022). "It was highly expressed in liver cancer and closely related with differentiation, dissemination, and serum AFP." (PMID 35586205, 2022). "Three combination regimens containing L-OHP and EPI (L-OHP + EPI + irinotecan + 5-FU, L-OHP + EPI, and L-OHP + irinotecan + EPI) also had greater inhibitory effects in AFP-positive than in AFP-negative liver cancer cells." (PMID 35127582, 2022). "Alpha-fetoprotein (AFP) is widely-known as the most commonly used protein biomarker for liver cancer diagnosis at the early stage." (PMID 36290918, 2022). "The sensitivities of liver cancer cells to combination regimens in the current study were all closely related to AFP." (PMID 35127582, 2022). "Risk prediction models could estimate individual patients’ risk of developing liver cancer and identify those at high risk from the primary care population (risk stratification) for active surveillance (screening) using liver ultrasonography and serum alpha-fetoprotein (AFP) test." (PMID 36261855, 2022). "GP-73 is a type 2 Golgi transmembrane glycoprotein that has been reported to yield a higher sensitivity of 77.4-86.3% but a lower specificity than AFP assay in the early diagnosis of primary liver cancer." (PMID 35401747, 2022). "A series of studies have reported that AFP levels and satellite nodules are related to worse survival of liver cancer patients." (PMID 36091153, 2022). "Alpha-fetoprotein (AFP)-positive liver cancer cells were significantly more sensitive to gemcitabine than AFP-negative cells (χ2 = 6.102, P=0.014)." (PMID 35127582, 2022). "The immunosensor from this study is an alternative tool to detect the AFP biomarker for clinical liver cancer diagnosis and monitoring, and it can be further developed for the electrochemical assays of other tumor indicators." (PMID 36389169, 2022). "Levels of liver cancer biomarkers such as alpha fetoprotein (AFP), alpha-fucosidase (AFU), and carcinoembryonic antigen (CEA), which are significantly increased by HCC, were depleted in the Hemimycale arabica and Negombata magnifica mesohyls groups." (PMID 36296934, 2022). "At present, screening for liver cancer mainly relies on imaging, such as computed tomography, magnetic resonance imaging, and tumor markers, especially α-fetoprotein (AFP)." (PMID 35943150, 2022). "Like liver cancer biomarker AFP, a clinical biomarker should have high specificity and sensitivity and is also detectable due to its peripheral distribution." (PMID 35395937, 2022). "The specificity and sensitivity of alpha-fetoprotein for liver cancer has made it an important indicator for liver cancer screening and diagnosis, but only 15–30% of liver cancer patients have significant changes in AFP in the early stage." (PMID 35712125, 2022). "Although AFP-L3 has higher diagnostic efficacy than AFP in liver cancer, AFP still has a good diagnostic value in some specific types of liver cancer, such as HBV-associated liver cancer." (PMID 35307694, 2022).
liver cancer (continued). "This study found that the combined detection of contrast-enhanced ultrasound and enhanced CT, AFP, and CA199 has a high diagnostic value for the early diagnosis of liver cancer." (PMID 35237392, 2022). "More and more researchers have paid attention to the role of abnormal glycosylation in tumors, such as alpha-fetoprotein (AFP), which is a clinically commonly used diagnosis of liver cancer." (PMID 36010914, 2022). "At present, b-ultrasound and serum alpha-fetoprotein are commonly used for screening and detecting liver cancer." (PMID 36096917, 2022). "High AFP levels were also associated with an incomplete tumor capsule, microvascular invasion (MVI), and Barcelona Clinic Liver Cancer (BCLC) C stage." (PMID 36258212, 2022). "AFP has been used as a serologic diagnostic biomarker for primary HCC, as it was found to be elevated in patients with liver cancer in the 1970s." (PMID 35307694, 2022). "It is efficient in the early warning of liver cancer metastasis and recurrence, achieving it 4.8 months earlier than imaging and 8.5 months earlier than AFP." (PMID 36175957, 2022). "The abnormal level of AFP in plasma is closely related to the malignancy of liver cancer, but due to insufficient sensitivity and specificity, the effect of early diagnosis of liver cancer is still not ideal." (PMID 36157238, 2022). "The results showed a significant correlation between AFP expression and gemcitabine sensitivity, with AFP-positive liver cancer cells being significantly more sensitive to gemcitabine than AFP-negative cells." (PMID 35127582, 2022). "miRNA7 TM Technology has higher sensitivity than that of AFP above 30%, a commonly used tumor marker of liver cancer, and its specificity is up to 90%." (PMID 36175957, 2022). "AFP plays a guide role in the diagnosis of liver cancer, but its sensitivity and specificity are poor." (PMID 36110223, 2022). "Many authoritative experts and organizations have designated AFP as the only tumor marker for primary liver cancer." (PMID 35464224, 2022). "Nevertheless, the increasing AFP concentration in adult serum leads to various diseases, including liver cancer." (PMID 36431072, 2022). "AFP is a specific tumour marker for the diagnosis of primary liver cancer but can show a high concentration when a variety of tumours occur." (PMID 36755860, 2022). "In HCC patients, AFP can be reactivated to participate in the regulation of liver cancer pathogenesis and the regulation of chemotherapy sensitivity, and is a classic marker of liver cancer." (PMID 36096917, 2022). "At present, AFP is still the most widely accepted serum biomarker in liver cancer in monitoring and diagnosis." (PMID 35359408, 2022). "AFP-positive liver cancer cells were significantly more sensitive to oxaliplatin (L-OHP) + epirubicin (EPI) + irinotecan + 5-fluorouracil (5-FU) and L-OHP + irinotecan + EPI." (PMID 35127582, 2022). "Multivariate Cox regression analyses identified that AFP, FAR, clinically significant portal hypertension, tumor size, Barcelona Clinical Liver Cancer staging system, major resection and blood loss were independent indicators for predicting OS and DFS." (PMID 35606690, 2022). "All of these markers are useful in the diagnosis, management, and prognosis prediction of liver cancer, especially the combination of AFP and DCP." (PMID 35547447, 2022). "In patients with liver cancer, the correlations between serum IL‐18 concentration and alanine aminotransferase, GT, LD, prealbumin, a‐fucosidase, alpha‐fetoprotein, hyaluronic acid, laminin, N‐terminal type III procollagen, and type IV collagen were analyzed." (PMID 33720453, 2021). "Numerous predictors related to the prognosis of liver cancer, such as AFP levels, tumor number, and tumor size, have been reported, but no effective indicators have been found to date." (PMID 34422654, 2021). "The SERS chip was decorated for the detection of the liver cancer cell marker Alpha-fetoprotein (AFP) with the detection limit down to 5 pg/mL." (PMID 33920637, 2021).
liver cancer (continued). "Patients had advanced disease of mostly Barcelona Clinic Liver Cancer Stage C (7, 87.5%), and a significant proportion had portal vein involvement (3, 37.5%) and AFP ≥400 ng/ml (6, 75%), and had received prior sorafenib treatment (5, 62.5%)." (PMID 33811482, 2021). "Alpha-fetoprotein (AFP) is the most commonly used tumor marker in the screening and clinical diagnosis of patients with liver cancer." (PMID 34348726, 2021). "AFP has been of great clinical value in both preoperative and postoperative surveillance for liver cancer, and has been used to clinically and serologically diagnose HCC for more than 20 years." (PMID 34696675, 2021). "AFP is closely related to the occurrence and development of liver cancer and a variety of tumors, mainly used as a serum marker for the diagnosis of primary liver cancer in clinical practice." (PMID 33869206, 2021). "AFP is an important serological indicator of liver cancer and a glycoprotein, with the synthesis and degradation of sugar chains completed inside the cell." (PMID 34475930, 2021). "In this study, on the one hand, we collected serum AFP and sICAM-1 levels of pre- and postoperative patients to assess their relationship with liver cancer recurrence and survival rate." (PMID 34696675, 2021). "The SERS chip was made for detecting the liver cancer cell marker AFP, and the detection limit of AFP in the range of 5 pg to 5 ng/mL was obtained, which provided a possible early detection of liver cancer." (PMID 33920637, 2021). "Immunofluorescence staining showed highly positive staining signals with liver cancer cells (AFP), iPSC-EC (hCD31), and iPSC-MC (vimentin) in vitro." (PMID 34439154, 2021). "Bone metastasis, portal vein tumor thrombus, alpha-fetoprotein and radiation dose are independent prognostic factors for the survival of advanced liver cancer patients treated with palliative radiotherapy." (PMID 34395242, 2021). "SERS was used as an active chip for detecting the liver cancer cell marker AFP due to its excellent performance." (PMID 33672380, 2021). "Alpha-fetoprotein (AFP) is currently the only clinically used biomarker for the early diagnosis of liver cancer." (PMID 34238253, 2021). "Serum AFP has been widely used as a non-invasive biomarker for the diagnosis of liver cancer, but it has been demonstrated to show poor sensitivity." (PMID 33391469, 2021). "Since AFP is a serum marker of primary liver cancer, we evaluated the AFP content in mouse serum using ELISA and found that serum AFP level of HBP1-deficient mice was higher than that of wild-type mice." (PMID 33794968, 2021). "In liver cancer diagnosis, AFP is a traditional biomarker, and the expression of GPC3 can distinguish benign nodular liver tumor with AFP negative." (PMID 34200243, 2021). "Fifty-seven patients were diagnosed as positive for primary liver cancer from serum AFP, of which seven had false positive results." (PMID 34475930, 2021). "As mentioned, the standard and the most commonly used biomarker for patients at risk of liver cancer, especially HCC, is AFP." (PMID 34440168, 2021). "AFP, currently the most commonly used clinical biomarker in liver cancer, has inadequate specificity." (PMID 34771525, 2021). "The immunofluorescence staining showed that highly positive staining signals with liver cancer cells (AFP), and proliferate cell (Ki67) and MC (vimentin)." (PMID 34439154, 2021). "Both in vitro and in vivo studies revealed that MPDA@SPIO/SA-PEI/AFP-Fth had excellent targeting ability and transfection ability towards hepatic cancer." (PMID 33731140, 2021). "AFP and sICAM-1 are specific indicators used to diagnose liver cancer or evaluate tumor invasiveness." (PMID 34696675, 2021).
liver cancer (continued). "Serum AFP for the diagnosis of primary liver cancer had a sensitivity of 83.02%, a specificity of 81.08%, and an accuracy of 82.22%." (PMID 34475930, 2021). "The regulatory mechanism of icaritin in AFP protein down-regulation provides a theoretical and experimental basis for further research into new drugs for the treatment of liver cancer." (PMID 33765973, 2021). "Alpha-fetoprotein (AFP) is controversial for its clinical application in the clinical detection of liver cancer." (PMID 33889548, 2021). "For example, silencing AFP expression induces growth arrest and apoptosis in human Huh 7 liver cancer cells." (PMID 33765973, 2021). "On the other hand, with regard to tumor factors, the patients who underwent RFA-TACE had higher levels of serum AFP and a larger proportion of multinodularity and Barcelona Clinic Liver Cancer (BCLC) stage 0." (PMID 33685409, 2021). "Our results showed TrxR had superior performance for discriminating between liver cancer patients and healthy controls than AFP, CEA, and CA19-9." (PMID 33727662, 2021). "In addition to being an oncofoetal antigen and diagnostic indicator for liver cancer, AFP also had multifarious biological functions, such as regulation of cell differentiation, proliferation, and tumorigenesis, and in fact, AFP could be used as an immunotherapeutic target for HCC." (PMID 34696675, 2021). "For example, AFP combined with either the lens culinaris lectin or the Golgi protein 73 could increase the diagnostic specificity, sensitivity and accuracy rate, greatly improving the early diagnosis rate of liver cancer, which was consistent with our findings." (PMID 34696675, 2021). "For example, PSA and AFP have been used as conventional biomarkers for the diagnosis of prostate and liver cancer, respectively." (PMID 34950253, 2021). "From serum AFP diagnosis, 57 patients had positive results for primary liver cancer, of which seven had false positive results, with a sensitivity of 83.02%, the specificity of 81.08%, and an accuracy of 82.22%, respectively." (PMID 34475930, 2021). "Rats induced to develop liver cancer exhibited an obvious increase in serum AFP, CEA, and CA19.9 levels." (PMID 34866538, 2021). "The BCLC staging system and AFP level have been proven to be efficient in predicting the survival of liver cancer." (PMID 34532340, 2021). "Although regular ultrasound and serum alpha-fetoprotein (AFP) levels are monitored in high-risk populations, it is reported that 70% of HCC patients are diagnosed in the intermediate Barcelona Clinic Liver Cancer (BCLC) stage or advanced (BCLC stage C) stage." (PMID 33738247, 2021). "CA-125, CA-199, and CA-153 are markers for ovarian, pancreatic or gastrointestinal, and breast cancer, respectively, while AFP is a tumor marker characteristic of liver cancer." (PMID 34595214, 2021). "AFP is a well-known biomarker for HCC, and CAR T-cell therapy targeting the AFP-MHC complex showed robust antitumor activity in AFP-CAR T cells in a mouse xenograft model of liver cancer." (PMID 33854960, 2021). "An elevated level of AFP is being reported in about 70% of the people being diagnosed with the primary liver cancer." (PMID 34327239, 2021). "In the 1970s, a series of large-scale screening programs for early diagnosis and treatment of liver cancer measuring serum alpha-fetoprotein (AFP) were carried out." (PMID 33604165, 2021). "At present, many studies have found that des-γ-carboxy prothrombin (DCP) [also known as protein induced by vitamin K absence or antagonist (PIVKA) II] and AFP-L3/AFP assessments can improve the sensitivity and specificity of early liver cancer diagnosis." (PMID 34277397, 2021). "As the earliest discovered tumor marker, alpha-fetoprotein (AFP) has become the main screening index for primary liver cancer." (PMID 33162827, 2020).
liver cancer (continued). "Specifically, 20 out of 31 liver cancers patients with high serum AFP levels belonged to iClust1, which ranked lowest in prognosis of all three subtypes." (PMID 31897235, 2020). "Among the available immunotherapies for liver cancer using AFP as a target, therapies using dendritic cells (DCs) stimulated with AFP-derived epitopes and vaccine therapies by class I-restricted peptides have been developed." (PMID 32132566, 2020). "The Chinese Liver Cancer Diagnosis and Treatment Guidelines recommend ultrasound combined with serum AFP levels as monitoring methods." (PMID 33015170, 2020). "As hypo-methylation of promoter is a common mechanism for gene activation in cancer, we checked methylation of AFP in normal liver and liver cancer." (PMID 31897235, 2020). "AFP is not only potential in early detection but allso is useful for liver cancer diagnosis as a general serum marker." (PMID 32433581, 2020). "Survival after correction for lead-time in the AFP group also revealed similar trends in patients with liver cancer as were observed in the entire cohort." (PMID 32845895, 2020). "Currently, clinical screening methods for early liver cancer mainly include the detection of serum α fetoprotein (AFP) and ultrasound examination of the liver." (PMID 32090248, 2020). "Methylation analysis revealed de-methylation of AFP promoter occurred in some liver cancer tissues, which was significantly related to AFP mRNA expression." (PMID 31897235, 2020). "Tumor subjects in our study were HBV-related primary liver cancer, then immunofluorescence assay and chemiluminescence immunoassay were used to measure AFP and PIVKA-II respectively." (PMID 33292429, 2020). "Although the transcriptional control of AFP expression is evident, it's unclear how liver cell cease expressing AFP after birth, and how AFP expression is re-activated in liver cancer." (PMID 31897235, 2020). "This was confirmed by an independent dataset in which liver cancer patients with high serum AFP also had poorer survival (Log-rank test: p = 0.024)." (PMID 31897235, 2020). "An increasing number of liver cancer biomarkers with high sensitivity and specificity, such as AFP isoform 3 (AFP-L3), have been identified and routinely applied in clinical testing." (PMID 32090248, 2020). "Examples include treatment of EGFR-mutation–positive lung cancer with mutant-EGFR–targeted inhibitors, or elevation of AFP as an indicator of liver cancer." (PMID 32993581, 2020). "For instance, alpha-fetoprotein (AFP), which rapidly decreases in serum after birth and is maintained at a low level throughout adulthood, is the most widely used biomarker for liver cancer (Spangenberg, Thimme & Blum, 2006)." (PMID 32095334, 2020). "AFP ≥ 400 ng/mL is recommended as the diagnostic criteria of HCC in the Chinese guideline for diagnosis and treatment of primary liver cancer (2017 edition)." (PMID 32053643, 2020). "Whole transcriptome analysis revealed that serum AFP levels clearly separated liver cancer into two classes with distinct expression profiles according to PCA analysis." (PMID 31897235, 2020). "The results suggest that INHA was associated with significant lower OS and RFS rate compare with TIVA in several sub-variable groups indicating more severe liver cancer status, including tumor diameter ≥ 10 cm; AFP ≥ 400μg/L; PVTT typeIIand PVTT typeIII." (PMID 32928121, 2020). "Previous studies found that extracellular AFP is able to promote the expression of FasL and inhibit the elevated Fas in Bel 7402 cells co-cultured with Jurkat cells, thus triggers the escape of liver cancer cells from immune surveillance." (PMID 33009373, 2020). "In conclusion, this study indicates that AFP re-activation is a result of the systematic transcriptome change, which collectively define a molecular subtype of liver cancer." (PMID 31897235, 2020).